AXIN2 (axin 2)
Diseases named in the same sentence as AXIN2 in open-access papers (continued):
Sharing a sentence is not in itself a finding about the gene and the disease.
prostate carcinoma (11 papers, 2008 to 2024). A carcinoma that arises from epithelial cells of the prostate gland. "For example, the SNV rs2240308 in the AXIN2 gene has been associated with an increased risk of BC, as well as colorectal and prostate cancers in various populations." (PMID 39710803, 2024). "The two AXIN2 mutations (c.2347G>T and c.1102G>A) were previously addressed as being associated with small cell lung and prostate cancers, respectively, while the FZD3 mutation (c.674dupT) was previously reported in oral squamous cell carcinoma (OSCC)." (PMID 35723313, 2022). "Significant racial differences have also been observed in the association between the AXIN2 rs2240308 polymorphism and the risk of prostate cancer." (PMID 26161041, 2015). "In conclusion, the present study demonstrates that there is a significant association between the rs2240308 SNP (G/A) of the Axin2 gene and the risk of prostate cancer." (PMID 25013500, 2014). "The present study investigated the association between the rs2240308 SNP (G/A) of the Axin2 gene, a regulator of Wnt signaling, and the incidence of prostate cancer." (PMID 25013500, 2014). "The present study evaluated the association between the Axin2 single nucleotide polymorphism (SNP) rs2240308 [guanine (G)/adenine (A)] and the incidence of prostate cancer." (PMID 25013500, 2014). "In order to determine any association between the Axin2 polymorphism and the risk of prostate cancer, the present study focused on rs2240308 (G/A) and compared the polymorphic region between 103 patients with prostate cancer and 100 control males." (PMID 25013500, 2014). "Axin2 expression was found upregulated in the majority of human prostate cancer cell lines examined." (PMID 18478098, 2008). "This association indicates the possibility that the variance in the Axin2 gene in this position may play a significant role in promoting the development of prostate cancer." (PMID 25013500, 2014). "The results revealed a higher incidence of prostate cancer in the subjects with the homozygous GG genotype and a reduced cancer incidence in the patients with the GA genotype of the rs2240308 SNP (G/A) in the Axin2 gene." (PMID 25013500, 2014). "To determine whether Wnt signaling plays a role in prostatic tumorigenesis and tumor progression, we assessed the Wnt signaling status in human prostate cancer cell lines and 2 human prostate tumor xenografts by measuring expression levels of Axin2." (PMID 18478098, 2008).
liver cancer (9 papers, 2010 to 2024). An epithelial or non-epithelial malignant neoplasm that arises from the liver. "The mutation and abnormality of AXIN2 (Axis inhibition protein 2) can lead to the occurrence of ampullary carcinoma, endometrial cancer, and liver cancer by adjusting the stability of beta-catenin." (PMID 35174154, 2021). "Our results confirm Wnt responsiveness of AXIN2, while BCL9 and BCL9L seem not to be Wnt-responsive in liver cancer cells." (PMID 31440992, 2020).
Oral leukoplakia (8 papers, 2020 to 2025). A thickened white patch on the oral mucosa that cannot be rubbed off. "In our previous study, we also found that overexpression of Axin2 and Snail is a potential risk factor for the malignant conversion of oral leukoplakia." (PMID 35875099, 2022). "Associations were also identified for a number of other markers such as between two markers in RHEB and leukoplakia of the oral mucosa and two markers in AXIN2 and loss of teeth/edentulism and, both phenotypes unique to the cancer-affected group." (PMID 32184411, 2020). "Moreover, increased levels of AXIN2 were highly correlated with the malignant transformation of an oral leukoplakia in humans, indicating possibly similar associations in canine oral tumors." (PMID 34072517, 2021). "In our previous study, we found that Axin2 expression showed a positive correlation with Snail expression, and increased expression of both Axin2 and Snail was closely associated with the malignant transformation of oral leukoplakia." (PMID 33046030, 2020). "In our previous studies, we found that the Axin2–Snail axis is significantly related to malignant transformation of oral leukoplakia." (PMID 35875099, 2022). "Moreover, increased expression of AXIN2 has been strongly correlated with the malignant transformation of oral leukoplakia." (PMID 40960755, 2025). "In addition, overexpression of both Axin2 and Snail can be found in some precancerous lesions, including colorectal adenoma and oral leukoplakia." (PMID 35875099, 2022).
endometrial cancer (7 papers, 2019 to 2023). Primary or metastatic malignant neoplasm involving the endometrium (mucous membrane that lines the endometrial cavity). "Both AXIN1 and AXIN2 are mutated in approximately 14% of uterine endometrial cancers and AXIN2 is mutated in about 5% of CRC patients." (PMID 37048063, 2023). "The expression of PMS2 mutation has been found to increase the risk of endometrial cancer and AXIN2 polymorphisms may activate the Wnt pathway associated with reproductive tract carcinomas." (PMID 32545766, 2020). "Recent studies identified Axin2, a classical Wnt reporter gene as a robust stem-cell marker in endometrial cancer." (PMID 34400617, 2021).
glioma (7 papers, 2015 to 2022). A benign or malignant brain and spinal cord tumor that arises from glial cells (astrocytes, oligodendrocytes, ependymal cells). "Western blot results showed that overexpression of Rab23, LCA alone, and combined treatment can downregulate β-catenin and c-myc protein levels in glioma U251 cells, which can upregulate GSK3β and Axin2 protein levels." (PMID 35497928, 2022). "The wingless or WNT pathway is implicated in development and stemness and has been associated with glioma stem-like cells and glioma pathobiology in which growth behavior, WNT activity, and cytoplasmic/nuclear β-catenin correlate with AXIN2 expression and poor patient outcome." (PMID 35717443, 2022). "IF and WB assays indicated that CUX1 regulated the distribution of Axin2/β-catenin in glioma cells and regulated the expression of proteins downstream of the Wnt/β-catenin signaling pathway, suggesting that CUX1 served as an upstream positive regulator of the Wnt/β-catenin pathway." (PMID 34422906, 2021). "Consistently, MAGI3 overexpression in glioma cells C6 suppressed expression of β-catenin target genes including Cyclin D1 and Axin2, whereas MAGI3 knockdown in glioma cells U373 and LN229 enhanced their expression." (PMID 26452219, 2015). "NEAT1 may interact with EZH2 and mediate H3K27 trimethylation in their promoters, and NEAT1 was essential for glioma cell proliferation and invasion, since it increased β-catenin nuclear transport while decreasing ICAT, GSK3B, and Axin2 expression." (PMID 37305396, 2021). "Moreover, NEAT1 was critical for glioma cell growth and invasion by increasing β-catenin nuclear transport and down-regulating ICAT, GSK3B, and Axin2." (PMID 32443824, 2020).
ectodermal dysplasia (6 papers, 2014 to 2025). "Among them, 47 (65.3%) were generally healthy and seven (9.7%) had a genetic disorder or a syndrome: Axin2 mutation, Becwith-Wiedemann syndrome, Incontinentia pigmenti, ectodermal dysplasia, and Williams syndrome." (PMID 40792598, 2025). "It remains to be defined whether ectodermal dysplasia is indeed due to the AXIN2 mutation as this is the only family reported to date with clear features of ectodermal dysplasia." (PMID 37626374, 2023). "AXIN2 pathogenic variants are associated with the absence of permanent teeth (hypodontia), sparse hair and eye brows (ectodermal dysplasia), and gastrointestinal (GI) polyps and cancer." (PMID 32807118, 2020). "Pathogenic AXIN2 variants cause absence of permanent teeth (hypodontia), sparse hair and eye brows (ectodermal dysplasia), and gastrointestinal polyps and cancer." (PMID 32807118, 2020).
hepatoblastoma (6 papers, 2010 to 2025). Hepatoblastoma (HB) is a malignant hepatic tumor and is the most common pediatric liver cancer. "Conversely, in hepatoblastoma, WNT pathway dysregulation often arises from mutations in CTNNB1 as well as deletions or the epigenetic silencing of AXIN1 and AXIN2, which act as negative regulators of the pathway." (PMID 39851951, 2025). "All tumoroids at early passage showed expression of known hepatoblastoma markers, AFP, DLK1, and the Wnt target gene, AXIN2." (PMID 39567523, 2024). "As a control, spatial transcriptomic analyses of a section of normal liver from a patient with hepatoblastoma showed very low expression of FGF19, AXIN2, and SOX4, without apparent co-localization." (PMID 39567523, 2024).
Stroke (6 papers, 2012 to 2024). Sudden impairment of blood flow to a part of the brain due to occlusion or rupture of an artery to the brain. "Exosomes delivering Zeb2/Axin2 have been shown to enhance post-stroke neuroplasticity, increase neurogenesis, and boost the concentration of BDNF." (PMID 39095888, 2024). "Associated cardiovascular diseases include diabetes (PDLIM5, HDAC4, and TLE1), cardiac development (PDLIM5) and myocardial aging (CASP12), hypertension (PFKP and TAB2), and intracerebral and intraventricular bleeding (RUNX1) and stroke (AXIN2)." (PMID 36620623, 2022). "Furthermore, increasing evidence suggests Zeb2/Axin2’s role in neurogenesis contributes to post-stroke functional recovery." (PMID 39095888, 2024). "For stroke, Apcdd1, Atp2b2, Axin2, ITIH-5 and Slc1a1 are specifically expressed in brain vasculome." (PMID 23285140, 2012).
leukemia (5 papers, 2015 to 2024). A malignant (clonal) hematologic disorder, involving hematopoietic stem cells and characterized by the presence of primitive or atypical myeloid or lymphoid cells in the bone marrow and the blood. "The chemo-resistant properties of MDR leukaemia cells are diminished by the suppression of miR-1246, which modulates AXIN2 and GSK-3β, leading to the deactivation of the Wnt/β-catenin signalling pathway." (PMID 39679367, 2024). "Based on this, we draw the following conclusions, miR-1246 influences chemo-sensitivity of leukemia cells via Wnt/β-catenin pathway by directly targeting AXIN2 and GSK-3β." (PMID 34093820, 2021). "So, the present work prospectively proved that miR-1246 could regulate chemo-resistant ability of leukemia cells via Wnt/β-catenin pathway by directly targeting AXIN2, GSK-3β and indirectly regulating P-gp expression." (PMID 34093820, 2021). "It is probable that blv-miR-B1-5p dysregulates AXIN2 to produce leukemia in cattle." (PMID 33195511, 2020). "The AXIN2 gene is the universal target of this pathway and is dysregulated in leukemia patients." (PMID 33195511, 2020). "In leukaemia cells, miR-1246 directly influences the 3′UTR seed-matching sites of AXIN2 and glycogen synthase kinase 3 beta (GSK-3β), worthwhile Wnt/β-catenin pathway participants." (PMID 39679367, 2024). "Both bioinformatics prediction and luciferase assay indicated that AXIN2 and glycogen synthase kinase 3 beta (GSK-3β) were the direct targets of miR-1246 in leukemia cells." (PMID 34093820, 2021). "Based on these, we inferred that miR-1246 regulated the activity of Wnt/β-catenin pathway by targeting AXIN2 and GSK-3β and lastly took part in ADM resistance regulation of leukemia cells." (PMID 34093820, 2021). "Inhibition of miR-1246 could up-regulate AXIN2 and GSK-3β and inactivate Wnt/β-catenin pathway, accompanied with inhibiting the expression of β-catenin and further influencing the expression of P-glycoprotein (P-gp) in the chemo-resistant leukemia cells." (PMID 34093820, 2021).
lung adenocarcinoma (5 papers, 2013 to 2023). A carcinoma that arises from the lung and is characterized by the presence of malignant glandular epithelial cells. "Results from in silico tools suggested that AXIN2 expressions in lung adenocarcinoma were lower than that in normal group." (PMID 31080360, 2019). "Results from in silico tools suggested that AXIN2 expression in normal group was higher than that in lung adenocarcinoma tissue." (PMID 31080360, 2019). "Furthermore, following a bioinformatics approach we generated a LEF1/TCF4 as well as an AXIN2 gene signature in cerebral metastases and investigated their prognostic value in a dataset of primary lung adenocarcinomas." (PMID 23224985, 2013). "Moreover, we explored whether the AXIN2 expression had an effect on the overall survival time of lung adenocarcinoma patients." (PMID 31080360, 2019). "In the H1703 human lung adenocarcinoma cell line, knockdown of PTPRK enhanced Wnt3a induced signaling in Topflash reporter assays as well as expression of the endogenous Wnt target gene AXIN2." (PMID 31934854, 2020). "Additionally, we generated a LEF1/TCF4 as well as an AXIN2 signature, the latter as representative of WNT/β-catenin activity, following a bioinformatics approach with a gene expression dataset of cerebral metastases in lung adenocarcinoma." (PMID 23224985, 2013).
breast tumors (4 papers, 2013 to 2022). "With regard to activation of the canonical Wnt pathway, we observed that RSPO3‐driven breast tumors expressed the Wnt/β‐catenin target genes Axin2, Wif1, Znrf3, and Ctnnb1 itself, however at significantly lower levels than their WNT1‐driven counterparts." (PMID 36106661, 2022). "Analysis of 965 primary breast tumors from TCGA RNA‐seq dataset showed that breast tumors harboring H1047R and other PIK3CA mutations (including E545K and E542K) have significant upregulation of AXIN2, HGF, STAT3, IGF‐1, and IGF‐2 mRNA compared with PIK3CA‐wild‐type and HER‐2‐amplified tumors." (PMID 28296140, 2017). "Additionally, AXIN2, the most reliable endogenous gene target of Wnt canonical pathway activation was markedly upregulated upon mRNA analysis of high-grade breast tumours." (PMID 23547709, 2013).
cleft lip (4 papers, 2014 to 2024). Congenital defect in the upper lip where the maxillary prominence fails to merge with the merged medial nasal prominences. "AXIN2 mutations have also been associated with the development of oral clefts, such as cleft lip and cleft palate." (PMID 34452579, 2021). "Eight significant variants associated with craniofacial malformations such as non-syndromic cleft lip and palate, mandibular prognathism, ocular abnormalities, and tooth defects are found in AXIN2, BMP2, BMP4, NOTCH3, PTCH1, SOX10, and WNT10A." (PMID 38785976, 2024). "This suggested relationship between AXIN2 and tooth agenesis also led to findings that AXIN2 gene variants may have a role in cleft lip/palate in multiple populations, with and without the presence of tooth agenesis as part of the clinical phenotype." (PMID 24607150, 2014).
colitis (4 papers, 2021 to 2024). Inflammation of the colon. "Knockout models have shown that myofibroblasts are the source of stromal Rspo3, which is essential for the regeneration and differentiation of Axin2- crypt cells after destruction of Lgr5+ and Axin2+ cells following colonic inflammation." (PMID 39461590, 2024). "Inhibiting of Pygo2 attenuated the development of MAT lesions in Il‐10−/−mice by promoting the differentiation of adipocytes, reducing inflammation, and leading to the amelioration of colitis partly through the Axin2/GSK3β pathway." (PMID 35707871, 2022). "The absence of Pygo2 attenuated the development of MAT lesions in Il‐10−/− mice by promoting the differentiation of adipocytes, leading to the amelioration of colitis partly through the Axin2/GSK3β pathway." (PMID 35707871, 2022). "The increase in Pygo2 may be related to mesenteric adipocyte poor differentiation and inflammatory features of CD, and Pygo2 inhibition could alleviate CD‐like colitis by improving mesenteric lesions by regulating the Axin2/GSK3β pathway." (PMID 35707871, 2022).
colorectal tumor (4 papers, 2019 to 2020). "The association of AXIN2 mutation with poor prognosis and its appearance in early stages, position it as a prognostic and predictive marker in the defined molecular subtype of right-side colorectal tumors with MSI." (PMID 31632692, 2019).
medulloblastoma (4 papers, 2009 to 2025). A malignant, invasive embryonal neoplasm arising from the cerebellum. "First of all, across 17 analyses, AXIN2 (Median rank 178, P < 0.05) was highly expressed in various tumors compared to normal tissue, while CASP9 (Median rank 28, P < 0.05) showed higher expression only in medulloblastoma in the Oncomine." (PMID 31681739, 2019). "Upregulation of AXIN2 in ITD-positive samples compared to the normal brain and a medulloblastoma of the SHH subtype was confirmed by qRT-PCR and was similar to the expression level found in a medulloblastoma of the WNT subtype." (PMID 27825128, 2016).
oral cancer (4 papers, 2014 to 2023). "AXIN2 functions as an oncogene; nevertheless, it has been revealed by multiple studies to exert oncogenic effects on colorectal and oral cancers." (PMID 38035113, 2023). "As a result, by western blot analysis, the protein expression level of β-catenin and the downstream targets such as DKK1 and Axin2 are highly upregulated in oral cancer SCC-55 cells compared to control cells." (PMID 34632073, 2021). "Later, the same group also established that miR-205 suppresses the oral carcinoma oncogenic activity via downregulation of Axin-2 in the KB human oral cancer cell." (PMID 33806361, 2021). "However, it is unclear how reduced Axin2 expression conferred by miR-205, rather than facilitates tumorigenesis as it usually does, contributes to the suppression of KB oral cancer cells." (PMID 24474204, 2014).
bladder cancer (3 papers, 2021 to 2025). "A previous study also showed the miR-1275/AXIN2 axis in bladder cancer tissues." (PMID 40476182, 2025).
colon adenocarcinoma (3 papers, 2015 to 2024). "Similarly, AXIN2 reveals the highest mutation rate in UCEC at 7.16%, with colon adenocarcinoma (COAD) showing a notable 5.67% mutation rate." (PMID 38291457, 2024). "Moreover, similar TCF4 silencing experiments performed in SW480 colon adenocarcinoma cells also decreased RHBG, Axin2 and Cyclin D1 mRNA levels." (PMID 26029888, 2015).
esophageal cancer (3 papers, 2019 to 2021). A primary or metastatic malignant neoplasm involving the esophagus. "To assess the influence of Wnt/β-catenin signaling in esophageal cancer cells, we first determined the expression levels of relevant Wnt-related proteins such as Axin2, active β-catenin (ABC), total β-catenin (TBC), and the Wnt-transcription factor TCF7L2 by Western blot analysis." (PMID 34638639, 2021). "The results showed a significant correlation between the expression levels of SPINK5 and β‐catenin (CTNNB1), LRP5, LRP6, DVL3, LEF1, AXIN2, MYC, and cyclin D1 (CCND1) in esophageal cancer." (PMID 30868765, 2019). "In esophageal cancer, the 5-year survival rate of high expression of PRR11 was significantly lower than that of the low expression group, which may be related to the interaction of PRR11 with destructive complexes (APC, GSK-3β and AXIN2) to activate the Wnt/β-catenin pathway." (PMID 34659555, 2021).
Familial adenomatous polyposis (3 papers, 2020 to 2025). Familial adenomatous polyposis (FAP) is characterized by the development of hundreds to thousands of adenomas in the rectum and colon during the second decade of life. "The known association between gastric adenomas and familial adenomatous polyposis, the other Wnt/beta-catenin disorder, supports the hypothesis that pathogenic AXIN2 variants increase risk as well." (PMID 32807118, 2020). "People with polyposis could have a genetic basis with germline mutations in polyposis-related genes, such as the APC gene, resulting in familial adenomatous polyposis (FAP), MUTYH-associated polyposis (MAP), or, rarely, in other genes such as AXIN2, GREM1, NTHL1, POLE, POLD1, or MSH3." (PMID 40095498, 2025).